GCG (glucagon)
Diseases named in the same sentence as GCG in open-access papers (continued):
Sharing a sentence is not in itself a finding about the gene and the disease.
Hypoglycemia (continued). "Despite low glucose alarms from her AHCL system, she did not awaken and was later discovered by her parents, who were alerted by the frequent alarming, and who subsequently injected her with intramuscular glucagon to treat the hypoglycaemia." (PMID 37864225, 2023). "The investigations in RIPGlut1; Glut2-/- mice showed that the glucagon secretion stimulated by hypoglycemia, as well as inhibitory effects of hyperglycemia on glucagon, disappeared." (PMID 37358764, 2023). "Since refractory hypoglycemia persisted 24 h after the insulin overdose, it was decided to proceed with glucagon treatment (15-30 ng/kg/min titrated to the blood glucose level after a loading dose of 50 ng/kg intravenous bolus infusion)." (PMID 38026640, 2023). "The first impact on the pancreas involves glucagon since these drugs lead to glycosuria, which can lead to hypoglycemia, resulting in a cascade requiring alpha cells to secrete glucagon for homeostasis." (PMID 36819350, 2023). "All counterregulatory hormones (glucagon, adrenaline [epinephrine], noradrenaline [norepinephrine], cortisol and growth hormone) increased during hypoglycaemia induction with both insulin products at both doses." (PMID 37308751, 2023). "This augmented glucagon release is believed to prevent hypoglycemia after protein intake, as AAs also stimulate insulin secretion." (PMID 37764697, 2023). "The emergence of nasal glucagon for hypoglycaemia resuscitation will make its administration by untrained individuals simpler and quicker so its inclusion on medical identification jewellery will be pertinent." (PMID 36334194, 2023). "For both of our patients, the diagnosis of HI was considered based on increased glucose requirements, the pattern of hypoketotic hypoglycemia, and the partial glycemic response to glucagon even though the elevated lactate was inconsistent with this disorder." (PMID 38027095, 2023). "As expected, hepatic glycogen concentrations were lower in FAST, and associated with diminished peak glucagon levels and reduced endogenous glucose production (EGP) during hypoglycemia." (PMID 37166980, 2023). "In T1D and late-stage (insulin deficient) T2D, the relationship between glucagon secretion and blood glucose levels is inverted, such that plasma glucagon levels rise after a mixed-meal and fall during hypoglycemia." (PMID 38298268, 2023). "Treatment with the CNS stimulant, modafinil, resulted in improved autonomic symptom scores, higher heart rates, higher glucagon concentrations during hypoglycemia, and improved scores on cognitive tests; however, the epinephrine response was not altered." (PMID 37942482, 2023). "The objective expert assessments used a standardized clinical case scenario of severe hypoglycemia and a practical demonstration of glucagon administration." (PMID 37628318, 2023). "In both patients, critical samples demonstrated hypoketotic hypoglycemia and a partial glycemic response to glucagon stimulation, thereby suggesting hyperinsulinism (HI)." (PMID 38027095, 2023). "Patients and their families are taught to monitor blood glucose levels, recognise the signs and symptoms of hypoglycaemia, and treat promptly with oral glucose or, in severe cases, intramuscular glucagon injection." (PMID 36334194, 2023). "When alive, both autopsied patients had inappropriately high insulin levels and lower free fatty acids in the setting of hypoglycemia with a positive glycemic response to glucagon stimulation." (PMID 38027095, 2023). "Both hormones are important in glycaemic control; glucagon reduces hypoglycaemia by stimulating hepatic glucose release in response to falling glucose levels, and amylin reduces post-prandial hyperglycaemia by delaying gastric emptying." (PMID 37289734, 2023). "Together, these morphological features enable rapid and robust glucagon secretory response to hypoglycaemia, fulfilling its role as an emergency counter-regulatory hormone." (PMID 37159865, 2023).
Hypoglycemia (continued). "At both hypoglycemia ranges, insulin boluses per kg of body weight used to induce hypoglycemia and plasma insulin and glucagon levels upon reaching hypoglycemia thresholds were comparable between arms." (PMID 37334295, 2023). "In the experiments, glucagon secretion remained unchanged in the isoglycemic-hyperinsulinemic response in the C-peptide infusion group, whereas it increased twofold during hypoglycemia." (PMID 37745697, 2023). "Hypoglycemia leads to a physiological response not only of counter-regulatory hormones such as glucagon, cortisol, catecholamines and growth hormone, but also of cytokines such as TNF-α, IL-6, IL-8 and VEGF-A." (PMID 37400734, 2023). "Half of the type 1 diabetes cohort comprised of adolescents and a patient with history of hypoglycemia—all showed an inverse relationship between glucagon and RAGE." (PMID 37558746, 2023). "For hypoglycemia, refractory to high-dose glucocorticoids, long-term intravenous glucagon infusion, or recombinant human growth hormone (prevents IGF binding to insulin receptors) is an option." (PMID 36779153, 2023). "If intact glucagon responses to hypoglycemia are required, then it is possible that any positive effect of feeding on CRR would be germane to individuals who are C-peptide positive." (PMID 37166980, 2023). "The rise in circulating glucagon after the consumption of HP meals has been proposed as a measure for preventing nocturnal hypoglycemia in people with T1D, and notably the HP meal also resulted in fewer hypoglycemic events than the HF meal in our study." (PMID 37513510, 2023). "Nevertheless, heterogeneous relationship between the glucagon response to insulin-induced hypoglycemia does exist but again is most evident in T1D with high levels of residual C-peptide." (PMID 36935525, 2023). "In the future, an ideal α-cell-targeted therapeutic would suppress glucagon secretion selectively under hyperglycemia, but permit secretion during hypoglycemia." (PMID 37152965, 2023). "For example, studies in dogs have shown that acutely increasing liver glycogen content, by an amount similar to what is seen over the course of a day with meals, increased glucagon and epinephrine responses to hypoglycemia, which doubled HGP." (PMID 37166980, 2023). "Apart from its insulin-stimulating effects, GIP, during hypoglycemia, stimulates glucagon secretion, enhances the absorption of fatty acids in adipocytes, increases the deposition of triglycerides in subcutaneous adipose tissue and decreases bone reabsorption." (PMID 37927592, 2023). "For glucagon, the pharmacodynamic (PD) profile (i.e., change in plasma blood glucose level) was also monitored in hypoglycemia‐induced rats." (PMID 37206225, 2023). "As the islet cells that produce glucagon, a principal counter-regulatory hormone, the α-cells play a vital role in the prevention of hypoglycaemia and the maintenance of systemic glucose homeostasis." (PMID 37159865, 2023). "This theory suggests that the cessation of insulin secretion from β cells in response to hypoglycemia, is a critical trigger for the rapid release of glucagon to raise blood glucose concentrations by gluconeogenesis." (PMID 37558746, 2023). "During hypoglycaemia, glucagon exposure was significantly lower in all surgical groups vs the non-surgical control group (all p<0.01)." (PMID 36648553, 2023). "She had frequent episodes of severe hypoglycemia (<50 mg/dL), one of which required administration of glucagon by paramedics." (PMID 37535407, 2023). "Generally, insulin output between meals is balanced by counteracting hormones such as glucagon and adrenaline to prevent overcompensation and hypoglycaemia." (PMID 36999224, 2023). "The glucagon response and, to a lesser extent, the growth hormone response to hypoglycemia displayed positive trends, whereas the ACTH/cortisol-response displayed negative trends with inflammatory responses (Supplement S4)." (PMID 37400734, 2023).
Hypoglycemia (continued). "Stimulation of glucagon secretion in hypoglycemia induces hepatic glucose production via cellular mechanisms, including suppression of glycogenesis and glycolysis and stimulation of glycogenolysis and gluconeogenesis." (PMID 37140984, 2023). "The glucose, glucose kinetics, and glucagon data were previously published as part of a report focusing on glucose counterregulatory response to insulin-induced hypoglycemia among GB and SG subjects." (PMID 35887007, 2022). "Especially during nights and rapid dips in glucose it is extremely important to be aware of the risk and start timely treatment with ingestion of fast absorbable carbohydrates or potentially glucagon to avoid severe hypoglycemia related complications." (PMID 36992787, 2022). "This is in line with the reported sympathetic response to insulin-induced hypoglycemia by increasing glucagon secretion." (PMID 36327900, 2022). "In healthy individuals, the alpha cells in the pancreatic islets of Langerhans secrete glucagon as a response to declining blood glucose concentrations to stimulate hepatic glucose output and prevent hypoglycaemia." (PMID 36213069, 2022). "This is especially important during the fasting period when glucagon secretion needs to prevent hypoglycemia development but when circulating free fatty acids increase." (PMID 36180454, 2022). "In summary, our study identified Agpat5 expressed in AgRP neurons as required for hypoglycemia-sensing by a population of AgRP neurons and for efficient triggering of glucagon secretion." (PMID 36180454, 2022). "We then performed hyperinsulinemic-hypoglycemic clamps to precisely control the level of hypoglycemia and measured the rate of glucose infusion required to maintain hypoglycemia, and the plasma glucagon concentrations at the end of the clamps." (PMID 36180454, 2022). "A previous genetic screen for hypoglycemia-induced glucagon secretion using a panel of 36 recombinant inbred BXD mouse lines identified a QTL on chromosome 85." (PMID 36180454, 2022). "It has been suggested that these patients have irregular glucagon secretion, which also contributes to hypoglycemia." (PMID 35813646, 2022). "We expected that plasma corticosterone, like glucagon, would also be elevated as part of a classic compensatory response to chronic hypoglycemia and metabolic stress." (PMID 35263131, 2022). "Studies have been conducted on dose-titrating regimens of glucagon infusion to achieve glycemic stability and avoid hypoglycemia in CHI patients, suggesting the potential of glucagon infusion as a therapeutic option for severe hypoglycemia in CHI patients." (PMID 36202918, 2022). "Further, 2-O-M significantly increased glucagon secretion and enhanced liver gluconeogenesis to prevent hypoglycemia." (PMID 35502441, 2022). "The fact that both insulin and glucagon concentrations were reduced suggests that the fetal hypoglycemia induced by SLC2A3 RNAi during the first half of gestation had an overall effect on pancreas development and growth, rather than a β cell-specific effect." (PMID 36293384, 2022). "We confirmed that Irak4, by modulating hypothalamic Il-1β signaling, indeed controls hypoglycemia-induced glucagon secretion." (PMID 36180454, 2022). "The vasopressin receptor V1b is expressed both on α and β cells and can regulate glucose homeostasis in a glucose-dependent way, which increases insulin during hyperglycemia and increases glucagon during hypoglycemia." (PMID 35669692, 2022). "The abnormal release of glucagon appears to be specific to hypoglycemia, however, since other conditions (like giving amino acids or withdrawing insulin and even physical activity itself) result in normal elevations of this hormone." (PMID 36992764, 2022). "Our physiological studies show that inactivation of Agpat5 in AgRP neurons suppresses their activation by hypoglycemia, impairs hypoglycemia-induced vagal nerve activity, and reduces glucagon secretion." (PMID 36180454, 2022).
Hypoglycemia (continued). "In T2D, miR-143-3p correlated negatively with glucagon at baseline (r2 = 0.22 and p = 0.04) and upon the hypoglycemia insult (r2 = 0.24 and p = 0.04)." (PMID 36499023, 2022). "Glucagon was correlated with the four miRNAs that were downregulated from the induction of hypoglycemia to 4 h later (miR-191-5p, miR-143-3p, let-7b-5p, and let-7g-5p)." (PMID 36499023, 2022). "It is initiated, in large part, by incompletely characterized brain hypoglycemia sensing neurons that trigger the secretion of counterregulatory hormones, in particular glucagon, to stimulate hepatic glucose production." (PMID 36180454, 2022). "Male and female Agpat5flox/flox and Sim1Agpat5KO mice displayed identical body weight, glucose tolerance, insulin sensitivity, and hypoglycemia-stimulated glucagon secretion." (PMID 36180454, 2022). "Glucagon, the counterregulatory hormone to insulin, increases in response to hypoglycemia and extended fasting to promote hepatic glycogenolysis and increase blood glucose." (PMID 36315375, 2022). "We demonstrated that Agpat5 inactivation in AgRP neurons led to reduced hypoglycemia-induced glucagon secretion." (PMID 36180454, 2022). "Reduced glucagon levels contribute to greater risks of HUA, nocturnal hypoglycemia and greater GV, while hyperglucagonemia predisposes to postprandial hyperglycemia and hypoglycemia awareness in patients with FCPD." (PMID 35819935, 2022). "Pancreas transplantation is considered a good option because the glucagon response to hypoglycemia can be restored simultaneously, preventing prolonged hypoglycemia." (PMID 35992127, 2022). "The glucagon dosages that have been used previously in SC bihormonal artificial pancreas devices to counteract hypoglycaemia resemble those we have used to demonstrate increased SC blood flow in healthy subjects." (PMID 36213069, 2022). "Here, using genetic mouse models, we demonstrate that Agpat5 expressed in agouti-related peptide neurons is required for their activation by hypoglycemia, for hypoglycemia-induced vagal nerve activity, and glucagon secretion." (PMID 36180454, 2022). "Optogenetic silencing of VMH SF1 neurons, or VMH neurons expressing neuronal nitric oxide synthase significantly blunted the glucagon response to hypoglycemia." (PMID 36327900, 2022). "The compatibility of insulin and glucagon also has to be determined in dual-hormone therapy to minimize the possibility of hypoglycemia." (PMID 36411933, 2022). "The main physiological function of glucagon is to maintain glucose homeostasis in cases of hypoglycemia." (PMID 36291711, 2022). "Given the immediate medical crisis that is created by hypoglycemia, losing the ability to secrete normal amounts of glucagon to counteract it is one of the most critical problems to address in the effective management of T1D." (PMID 36992764, 2022). "When hypoglycemia occurs, the repulsive cationic matrix can facilitate the release of glucagon for correcting dangerously low blood glucose." (PMID 35957510, 2022). "The current study is novel to evaluate the complex interrelationship between glucagon levels, glycemic variability and hypoglycemia unawareness in a cohort of patients with FCPD." (PMID 35819935, 2022). "Pharmacological or genetic inhibition of ACC1 resulted in impaired glucagon secretion at low glucose and in response to fasting or insulin-induced hypoglycaemia in vivo." (PMID 35304577, 2022). "While hypoglycemia stimulates the secretion of glucagon from pancreatic alpha cells to promote gluconeogenesis and glycogenolysis in the liver, glucagon’s role is more diverse." (PMID 36686477, 2022). "The α cells of the pancreatic islets secrete glucagon to raise blood glucose in response to hypoglycemia, and the δ cells secrete somatostatin to inhibit the secretion of both insulin and glucagon." (PMID 35669692, 2022).
Hypoglycemia (continued). "* When hypoglycemia occurs (either at rest or during physical activity), the release of glucagon is the key signal for the liver to either break down stored glycogen or use the process of gluconeogenesis to make and release glucose into the blood." (PMID 36992764, 2022). "Glucose increase is the principal determinant of GLP-1 increase with the consequent stimulation of insulin secretion, the latter balanced by a paradoxical glucagon increase that stimulates EGP to prevent hypoglycaemia." (PMID 33895917, 2022). "In a genetic screen of recombinant inbred BXD mice we previously identified Agpat5 as a candidate regulator of hypoglycemia-induced glucagon secretion." (PMID 36180454, 2022). "Nevertheless, hypoglycaemia still occurred towards the end of exercise with SSTR2a, and the induction of glucagon wavered in the post-exercise period when plasma glucose reached its nadir." (PMID 36147573, 2022). "Our data also demonstrated elevated levels of glucagon in response to hypoglycemia in control subjects as well as subjects with T2D." (PMID 36203210, 2022). "The data showed glucagon elevation in response to hypoglycemia in both the control and T2D cohorts, as would be expected in the counter-regulatory response." (PMID 36499023, 2022). "While normally functioning beta cells make and release insulin, pancreatic alpha cells are responsible for the production of the hormone glucagon, the release of which occurs in response to hypoglycemia and is suppressed by elevations in blood glucose." (PMID 36992764, 2022). "We next collected tail blood at 0 and 15 min during the ITT to assess the effect of calorie restriction on hypoglycemia-stimulated glucagon secretion." (PMID 36315375, 2022). "Agpat5 appeared as the most likely candidate regulator of hypoglycemia-induced glucagon secretion of the chromosome 8 QTL5." (PMID 36180454, 2022). "A glucose‐responsive glucagon microneedle patch is generated with this method for dealing with hypoglycemia emergencies." (PMID 35957510, 2022). "In hypoglycemia, the hormone glucagon is released from the pancreas and raises circulating glucose levels primarily via hepatic glycogenolysis, and to a lesser degree by gluconeogenesis in the liver." (PMID 36557261, 2022). "They demonstrated that administering 150 μg of subcutaneous glucagon was as effective as oral glucose tablets in managing mild to moderate hypoglycemia." (PMID 35345701, 2022). "In keeping with a role for VMH neurons, knockout of glutamate transporter, VGLUT2, in steroidogenic factor-1 (SF1) neurons (a major subset of VMH neurons) impairs the pancreatic glucagon response to fasting leading to hypoglycemia." (PMID 36327900, 2022). "It is interesting to note that in the experiment aimed at testing the effect of inactivating Cpt1a in AgRPAgpat5KO mice the glucagon response to hypoglycemia was only mildly reduced in the AgRPAgpat5KO mice." (PMID 36180454, 2022). "GIPR also stimulates the secretion of glucagon in hypoglycemic states and reduces the occurrence of hypoglycemia." (PMID 36119737, 2022). "All included studies used a combination of ICD codes and NLP to identify hypoglycemia; other methods were applied, including laboratory tests for plasma glucose measures ≤70 or <54 mg/dL and glucagon administration." (PMID 35576579, 2022). "Surprisingly, glucagon was significantly elevated prior to the development of hypoglycemia at 2 h, but then showed a high degree of variation among individual mice." (PMID 36548717, 2022). "Until recently, glucagon was considered a mere antagonist to insulin, protecting the body from hypoglycemia." (PMID 36686477, 2022). "Fourth, the markedly impaired glucose response to glucagon in patients with liver cirrhosis affects glucose release during hypoglycemia." (PMID 36687427, 2022).